WT1 (WT1 transcription factor)
Description:
Transcription factor that plays an important role in cellular development and cell survival. Recognizes and binds to the DNA sequence 5'-GCG(T/G)GGGCG-3'. Regulates the expression of numerous target genes, including EPO. Plays an essential role for development of the urogenital system. It has a tumor suppressor as well as an oncogenic role in tumor formation. Function may be isoform-specific: isoforms lacking the KTS motif may act as transcription factors. Isoforms containing the KTS motif may bind mRNA and play a role in mRNA metabolism or splicing. Isoform 1 has lower affinity for DNA, and can bind RNA.
Synonyms: WAGR; WIT-2; AWT1; NPHS4; WT-1; GUD; WT33
Tractability: PROTAC: UniProt records ubiquitination sites on it. Other modalities: a drug acting on it is in phase 2 or 3 trials.
Target class: Transcription factor
Gene: Protein-coding gene on chromosome 11 (32,387,775 to 32,435,564, reverse strand). Ensembl gene ENSG00000184937.
Subcellular location: Nucleus; Nucleus, nucleolus; Cytoplasm; Nucleus speckle (Isoform 1); Nucleus, nucleoplasm (Isoform 4)
Subcellular location (Human Protein Atlas): Nucleoplasm; Cytosol
Pathways (Reactome):
Developmental Biology: Nephron development; Transcriptional regulation of testis differentiation
Cell-Cell communication: Negative Regulation of CDH1 Gene Transcription
Gene Ontology:
Molecular function: C2H2 zinc finger domain binding; DNA-binding transcription activator activity, RNA polymerase II-specific; double-stranded methylated DNA binding; hemi-methylated DNA-binding; protein binding; RNA polymerase II cis-regulatory region sequence-specific DNA binding; sequence-specific DNA binding; transcription cis-regulatory region binding; zinc ion binding; DNA-binding transcription factor activity; DNA-binding transcription factor activity, RNA polymerase II-specific; sequence-specific double-stranded DNA binding
Biological process: adrenal gland development; branching involved in ureteric bud morphogenesis; cellular response to cAMP; cellular response to gonadotropin stimulus; glomerular basement membrane development; glomerulus development; heart development; kidney development; male gonad development; metanephric epithelium development; metanephric S-shaped body morphogenesis; negative regulation of apoptotic process; negative regulation of cell growth; negative regulation of cell population proliferation; negative regulation of DNA-templated transcription; negative regulation of gene expression via chromosomal CpG island methylation; negative regulation of transcription by RNA polymerase II; positive regulation of DNA-templated transcription; positive regulation of gene expression; positive regulation of miRNA transcription; positive regulation of transcription by RNA polymerase II; sex determination; visceral serous pericardium development; adrenal cortex formation; camera-type eye development; and 25 more
Cellular component: cytosol; nuclear speck; nucleoplasm; nucleus; cytoplasm; nucleolus
Genetic constraint (gnomAD): Loss-of-function variants: 8 observed, 56.94 expected, observed/expected ratio (o/e) 0.14, 90% interval 0.081 to 0.25. The upper end of that interval is the gene's LOEUF score, 0.25, which puts it in group 1 of 6, group 1 being the genes least tolerant of losing a copy. Missense variants: 568 observed, 668.59 expected, observed/expected ratio (o/e) 0.85, 90% interval 0.79 to 0.91. Synonymous variants: 312 observed, 272.25 expected, observed/expected ratio (o/e) 1.15, 90% interval 1.04 to 1.26.
Gene-disease validity (ClinGen):
ClinGen rates the evidence that WT1 causes each of these diseases.
Denys-Drash syndrome (autosomal dominant): Definitive. Denys-Drash syndrome (DDS) is a rare urogenital disorder characterized by the association of diffuse mesangial sclerosis (DMS), male pseudohermaphroditism with a 46,XY karyotype, and nephroblastoma.
Wilms tumor 1 (autosomal dominant): Definitive. An autosomal disorder due to pathogenic variants in the WT1 gene leading to an increased risk Wilms tumor and genitourinary abnormalities incorporating Denys-Drash syndrome and Frasier syndrome.
Cancer hallmarks: escaping programmed cell death (suppresses); genome instability and mutations (suppresses); suppression of growth (promotes); invasion and metastasis (promotes); angiogenesis; escaping programmed cell death (promotes); escaping immune response to cancer; proliferative signalling (promotes); change of cellular energetics; cell replicative immortality; cell replicative immortality (suppresses); angiogenesis (promotes)
Homologues: Orthologues: chimpanzee WT1 (98% identical), macaque WT1 (97% identical), dog WT1 (96% identical), pig WT1 (95% identical), mouse Wt1 (93% identical), rat Wt1 (93% identical), tropical clawed frog wt1 (68% identical), zebrafish wt1a (61% identical), guinea pig WT1 (58% identical), rabbit WT1 (57% identical). Paralogues in human: EGR2 (21% identical), EGR1 (19% identical), EGR3 (19% identical), EGR4 (16% identical).
Diseases named in the same sentence as WT1 in open-access papers:
WT1 is named in the same sentence as 478 diseases in open-access papers, as found by Europe PMC text mining. Sharing a sentence is not in itself a finding about the gene and the disease. The quoted sentences say what the papers report.
Wilms tumor (320 papers, 1993 to 2026). An embryonal neoplasm characterized by the presence of epithelial, mesenchymal, and blastema components. "We would expect that as in other instances of WT1-related disease, XX findings on karyotype are associated with a low risk of gonadoblastoma and although the risk of Wilms’ tumor remains in XX individuals, this is much more often observed early in life." (PMID 40235736, 2025). "Deletion of chromosome 11p13 underlies WAGR syndrome (Wilms tumor, Aniridia, Genitourinary anomalies, Range of developmental delay) that includes WT development due to WT1 inactivation." (PMID 40340749, 2025). "Our group also reviewed 126 cases with WT1 intron 9 variants, in which the prevalence of Wilms tumor was 3% (1/30 cases)." (PMID 39002031, 2025). "Although WT1-mutation-associated syndromes are the most common, Wilms tumors can be seen in a wide variety of CPS." (PMID 39847050, 2025). "Until recently, our understanding of genetic alterations associated with Wilms tumor was primarily confined to genes known to be involved in kidney development, such as WT1, as well as Wnt-activating mutations in CTNNB1 and AMER117." (PMID 40087269, 2025). "WT1 was first identified as a tumour suppressor gene in Wilms’ tumours but subsequent work showed that overexpression or mutation of WT1 contributes to tumorigenesis of some leukaemias and solid tumours." (PMID 40276932, 2025). "WT1 gene mutations have been implicated in the pathogenesis of Wilms tumor, particularly in syndromic cases such as WAGR syndrome and Denys-Drash syndrome." (PMID 40142302, 2025). "Only in one of the patients under observation was Wilms’ tumor diagnosed 2 years after the recognition of the WT1 pathogenic variant." (PMID 40332152, 2025). "The WT1 gene was isolated in 1990 as the causative gene of Wilms tumor and is located on chromosome 11p13." (PMID 39002031, 2025). "WT1 is crucial for kidney and genital development, with mutations causing cancers like Wilms tumors and genital dysgenesis." (PMID 40141456, 2025). "Among the patients we described, in three out of four children diagnosed with Wilms’ tumor, it was indeed the Wilms’ tumor that was the first manifestation of pathogenic variants in the WT1 gene." (PMID 40332152, 2025). "WT1 variants in the germline are known to cause Wilms tumor as well as renal glomerulosclerosis and gonadal dysplasia." (PMID 39002031, 2025). "Both the Children’s Oncology Group and other initiatives have elucidated genetic aberrations impacting many pathways crucial for kidney development and oncogenesis, finding that there are recurrent mutations in Wilms tumor of the WT1, CREBBP, and MLLT1 genes." (PMID 40142302, 2025). "Variants in the WT1 gene are linked to an elevated risk of developing Wilms’ tumor and gonadoblastoma, with FS carrying a moderate risk profile of 5%–20%." (PMID 40980126, 2025). "A child (PD49189) with an undiagnosed WT1 germline mutation and bilateral asynchronous Wilms tumours developed acute myeloid leukaemia." (PMID 39665570, 2025). "The Wilms Tumour gene 1 (WT1), initially identified in 1990 among patients with Wilms’ tumour, encodes a transcription factor characterized by a zinc-finger-like structure." (PMID 40980126, 2025). "The Wilms tumor 1 (WT1) gene was first identified in 1990 as a strong candidate for conferring a predisposition to Wilms tumor." (PMID 39002031, 2025). "Being alert about WT1 variants is especially important for girls with Wilms tumor who often miss additional phenotypes." (PMID 39698353, 2024). "In renal cancer, the WT1 gene mutation is one of the common genetic alterations and has been reported in several subtypes of renal cancer, including ccRCC and in particular nephroblastoma." (PMID 37999735, 2024).
Wilms tumor (continued). "The aniridia is due to PAX6 gene deletion, whereas Wilms tumor predisposition is due to WT1 gene deletion." (PMID 39600756, 2024). "Intriguingly, WT1 acts as a tumour suppressor in Wilms tumours—a rare form of childhood kidney cancer—through loss-of-function mutations and epigenetic silencing while it is also suggested to act as oncogene in several tumour types in adults." (PMID 39592856, 2024). "Patients with truncating variants in WT1 had the highest frequency of Wilms tumor occurrence (95%) and they often had bilateral tumors (56%)." (PMID 39698353, 2024). "A limitation of our study, however, is that the profound development defects and early lethality caused by mutant ENL expression in Wt1+ precursors preclude a direct assessment of its role in Wilms tumor formation, which typically manifests months after birth." (PMID 39009564, 2024). "The inactivation of WT1, the first identified tumor suppressor gene associated with Wilms tumor, is an important factor in Wilms tumor development." (PMID 39440064, 2024). "The Wilms tumor gene (WT1), typically associated with Wilms tumor, is found to be excessively expressed in some cancers, such as pancreatic cancer." (PMID 38665761, 2024). "Despite WT1 being well studied as a tumor suppressor gene, its role in non-WT1-mutated Wilms tumors and the corresponding implications on prognostic outcome remain ambiguous." (PMID 39272909, 2024). "In conclusion, we observed that patients with WT1 variants present a spectrum of phenotypes with a genotype-phenotype correlation for the risk of Wilms tumor development and age of onset of CKD." (PMID 39698353, 2024). "In hereditary Wilms tumors, clonal loss of WT1 impedes the β-catenin expression and leads to dysplastic nephrogenic rests." (PMID 38929279, 2024). "Various somatic mutations have been known to be associated with Wilms tumor—in particular, somatic WT1 mutations are observed in 10 to 20% of Wilms tumors in general." (PMID 39272909, 2024). "Early information on Wilms tumor-associated genes were identified in patients with tumor predisposition syndromes, highlighting the vital roles of Wilms tumor 1 (WT1), WTX, the WNT pathway and so on." (PMID 38937681, 2024). "Among patients with WT1 variants, a genotype-phenotype correlation was observed for Wilms tumor risk and age of CKD onset." (PMID 39698353, 2024). "Wilms' tumor gene 1 (WT1), which was once thought to be a tumor suppressor gene causing Wilms' tumor, is one of the most promising TAAs that has been identified as a target for cancer immunotherapy." (PMID 38665761, 2024). "WT1 disorder is a recently introduced term for phenotypes associated with germline Wilms Tumor 1 (WT1) variants, including glomerulopathy, urogenital anomalies, and Wilms tumor." (PMID 39698353, 2024). "At least 50% of the Wilms’ tumors with affected WT1 gene display acquired somatic mutations in CTNNB1 gene (Catenin Beta 1 gene), which is located on chromosome 3 (3p22.1)." (PMID 37176098, 2023). "A pathogenic variant in WT1 (c.1046del, p.(Leu349Profs*26)) was found in a patient with nephroblastoma (PaedCan01)." (PMID 37507557, 2023). "The WT1 gene is also involved in the development of a subtype of Wilms tumors, where inactivation/mutation of both alleles was identified." (PMID 36689432, 2023). "Hypospadias and Wilms’ tumour have been described together in genetic syndromes such as those resulting from mutations in the WT1 gene." (PMID 38020521, 2023). "Studies have shown that the Wt1 gene played an important role in normal genitourinary development and cancer development, and approximately 10% of Wilms’ tumors showed Wt1 mutations." (PMID 36829196, 2023). "Although WT1 was first identified via its genetic mutations in Wilms tumor (WT), a childhood malignancy of the kidneys, aberrant expression patterns of this gene have been observed in many types of solid cancers and even in a subset of WTs." (PMID 37444601, 2023).
Wilms tumor (continued). "The Wilms tumor one (WT1) gene encodes a transcription factor deeply involved in the regulation of a set of genes accountable for the development of healthy hematopoiesis and the normal development of the genitourinary tract." (PMID 37444601, 2023). "The typical histological characteristics and robust positive expression of WT1 in Wilms tumor match established diagnostic criteria." (PMID 38234938, 2023). "The assessment of serious cancerous tumors (e.g., Wilms’ tumor or gonadoblastoma in patients with WT1 mutations) can be potentially possible through genetic diagnostic tests for the primary analysis and disease monitoring of certain extra-renal phenotypes." (PMID 35022016, 2022). "Wilms tumour (WT) survivors, especially patients with associated syndromes or genitourinary anomalies due to constitutional WT1 pathogenic variant, have increased risk of kidney failure." (PMID 34608521, 2022). "Early identification of underlying WT1 pathogenic variant in a child with Wilms tumour has potential value in planning the surgical approach to nephron-sparing in relation to the anticipated decline in kidney function." (PMID 34608521, 2022). "wt1 was first identified as a tumor suppressor gene in Wilms’ tumor, a pediatric kidney tumor, and has been implicated in normal kidney development." (PMID 36412640, 2022). "WT1 was originally discovered as a tumor suppressor because of its loss-of-function mutations in a subset of pediatric renal neoplasms, known as nephroblastomas or Wilms’ tumors." (PMID 35465313, 2022). "Mutations of the Wilms tumor suppressor-1 gene (WT1) are associated with life-threatening glomerulopathy, disorders of sexual development, Wilm's tumor, and gonadal malignancies." (PMID 35498778, 2022). "The intron 9 splice site mutations of WT1 are associated with a high risk of gonadoblastoma and only rarely with Wilms tumor." (PMID 35211794, 2022). "wt1 was identified as a tumor suppressor gene in Wilms’ tumor, and approximately 15% of Wilms’ tumors have mutations in wt1." (PMID 36412640, 2022). "First, despite widespread WT1 detection in human Wilms tumor and associated patient-derived xenografts, WT1 expression was detected in only one Wilms tumor cell line (WiT49) in the current analysis." (PMID 35406427, 2022). "Thirty-seven percent of WT1-related SRNS showed genital abnormalities or a predisposition to Wilms tumor, 2 cases of SMARCAL1-related SRNS showed growth failure and poor cellular immunity." (PMID 35755072, 2022). "In contrast to these findings, the present study showed that knockdown of endogenous WT1 in WiT49 human Wilms tumor cells was associated with decreased TERT transcription." (PMID 35406427, 2022). "WT1 is a tumor suppressor gene and its homozygous loss is associated with Wilms Tumor, the most common kidney cancer in children." (PMID 36120564, 2022). "The risk of Wilm's tumor and gonadoblastoma in individuals with WT1 mutations is ominous and merits close surveillance for yet an undetermined period." (PMID 35498778, 2022). "Historically, there has been an unsubstantiated concession to perform prophylactic nephrectomies in young children with WT1 mutation, especially in the setting of prior Wilm's tumor or in preparation for transplantation." (PMID 35498778, 2022). "Diffuse expression of WT1 (Wilms' Tumor) is a useful diagnostic test in these cases, which was negative in our case." (PMID 35797874, 2022). "The p.R435X germline mutation in WT1 has been classified as pathogenic which is associated to Wilms tumor in the clinvar (RCV000003671)." (PMID 35896598, 2022). "WT1 is a tumor suppressor gene associated with the development of a Wilms’ Tumor, for which it was named." (PMID 33613644, 2021). "WT-1, originally discovered as a diagnostic marker for Wilms` tumor, is less sensitive than calretinin and D2-40 for peritoneal malignant mesothelioma but is more specific in distinguishing malignant mesothelioma from adenocarcinomas." (PMID 33432559, 2021).